TET2 (tet methylcytosine dioxygenase 2)
Diseases named in the same sentence as TET2 in open-access papers (continued):
Sharing a sentence is not in itself a finding about the gene and the disease.
lymphoma (77 papers, 2013 to 2026). A malignant (clonal) proliferation of B- lymphocytes or T- lymphocytes which involves the lymph nodes, bone marrow and/or extranodal sites. "Next-generation sequencing (NGS) of biopsy specimens from both lymphoma types revealed shared TET2 mutations." (PMID 41766912, 2026). "Among the potentially pathogenic changes predicted in CLP cells, TET2 mutation is the most frequent, seen in three of the four cases with divergent evolution of metachronous lymphomas, as well as in two of those with prior or subsequent biopsy showing HT." (PMID 39722652, 2025). "Rare constitutional TET2 variants have been reported to segregate with hematopoietic malignancy, including lymphoma and myeloid malignancy." (PMID 40116537, 2025). "Although TET2 mutations were initially associated with B-symptoms (p = 0.034) and lymphoma subtype (p = 0.045), these associations lost significance after Bonferroni correction for multiple comparisons." (PMID 41225024, 2025). "In TET2 knockout mice, loss of TET2 disrupts GC B cell homeostasis and promotes transformation into aggressive lymphomas." (PMID 40943058, 2025). "Stremenova‐Spegarova and colleagues investigated three cases of childhood immunodeficiency with concomitant lymphoma and identified rare biallelic TET2 variants in all three patients." (PMID 40116537, 2025). "Loss-of-function somatic mutations in TET2 are associated with various types of hematopoietic cancers in humans, including myeloid and lymphoid cancers as well as several solid cancers." (PMID 38605953, 2024). "TET2 and CREBBP mutations are, in the majority of cases, mutually exclusive, so TET2 loss-of-function generates lymphoma cells that show a dependence on HDAC3." (PMID 39518937, 2024). "Several studies have highlighted the characteristic mutational landscape of TFH lymphomas, which typically associates mutations in epigenetic regulators (TET2, DNMT3A, and IDH2), RHOA G17V, and alterations in the T-cell receptor (TCR) signaling pathway." (PMID 37500795, 2023). "Many studies have now established that up to 80% of patients with TFH lymphomas carry the same TET2 and/or DNMT3A mutations identified in the T-cells and the myeloid cells." (PMID 36793612, 2023). "The lymphoma shows increased expression of PD-L1, demonstrates frequent mutations of TET2 and PI3 Kinase." (PMID 37188189, 2023). "TET2 mutations are associated with clonal hematopoiesis and consistently patients with TET2-mutant lymphoma typically carry the identical mutation in their hematopoietic stem cells (HSCs)." (PMID 38124747, 2023). "Given that TET2 is the most commonly mutated epigenetic regulator in these lymphomas, this review will focus on the mechanistic role of TET2 in the development and treatment of nodal TFH lymphomas." (PMID 37841428, 2023). "TFH lymphomas frequently harbor TET2 and DNMT3A mutations, and identical mutations have been identified in both the malignant T-cells and the myeloid component of patients, suggesting a common ancestral clone with subsequent divergent evolution." (PMID 37646869, 2023). "We recently identified a family with lymphoma predisposition where a heterozygous truncating germline mutation in TET2 segregated with nodular lymphocyte-predominant Hodgkin lymphoma." (PMID 36639817, 2023). "Together these data strongly support a role for RhoA-G17V as a driving mutation in nodal TFH lymphomas but also speak to the requirement for concomitant TET2 loss in the hematopoietic compartment to promote lymphomagenesis." (PMID 37841428, 2023). "The extent to which TET2 mutations in the lymphoma microenvironment and responding immune cells contributes to T cell lymphomagenesis has not been fully elucidated." (PMID 37841428, 2023). "A murine model with a hypomorphic TET2 allele does develop TFH-like lymphomas but with a prolonged latency." (PMID 37841428, 2023).
lymphoma (continued). "TET2 deficiency in all hematopoietic cells accelerated the development of TFH lymphomas compared to either a wild-type hematopoietic compartment or TET2 deletion solely in T cells." (PMID 37841428, 2023). "In these various murine models, RhoA-G17V overexpression in T cells promoted TFH proliferation/expansion and the concomitant expression in the setting of hematopoietic TET2 deficiency led to the development of TFH lymphomas with varying penetrance." (PMID 37841428, 2023). "Three unaffected TET2 mutation carriers, two elderly mutation carriers previously affected by lymphoma, and three control individuals from the family participated in this non-randomized, open-label clinical trial of vitamin C on the DNA methylation load." (PMID 36639817, 2023). "From the initial identification of TET2 mutations in AITL and other nodal TFH lymphomas just over twenty years ago, significant strides have been made to advance the understanding of TET2’s role in the pathogenesis of these lymphomas." (PMID 37841428, 2023). "Namely, TET2 loss of function in the lymphoma microenvironment, which arises in the setting of clonal hematopoiesis, likely play a critical role in supporting TFH transformation and AITL development." (PMID 37841428, 2023). "This study suggests that: 1) TET2-CH was detected in 8.2% of patients with lymphoma; and 2) TET2-CH was associated with AIC in patients with lymphoma." (PMID 35492814, 2022). "In summary, in this exploratory analysis, TET2-CH was associated with AIC in patients with lymphoma." (PMID 35492814, 2022). "Strikingly, this reduction in Tet2 promoter to enhancer looping was associated with reduced abundance of Tet2 mRNA in Smc3/Bcl6 vs Bcl6 lymphomas from qPCR experiments performed in independent lymphoma specimens." (PMID 34621263, 2021). "The TET2 gene is subjected to frequent somatic mutations in an extensive range of hematopoietic cancers, including myeloid and lymphoid cancers and several solid cancers." (PMID 34948036, 2021). "The Tet2 gene is subjected to frequent somatic mutations in an extensive range of hematopoietic cancers, including myeloid and lymphoid cancer, and several solid cancers." (PMID 33184433, 2020). "DNMT3A and TET2 mutations are often co-identified in clonal hematopoietic cells in Tfh lymphoma patients." (PMID 32704161, 2020). "Since resemblance with AITL was striking, these authors analyzed the Tfh plck-GAPDH lymphoma cells for mutations in RhoA, Tet2, Idh2, and Dmt3a, frequently mutated in these patients." (PMID 32796826, 2020). "TET2 mutations were found in 14 out of 71 patients (20%), including 13/60 patients with an aggressive subtype (acute+lymphoma) and 1/11 patient with indolent subtype (chronic+smoldering)." (PMID 28881727, 2017). "Acquired TET2 mutations are also observed in lymphoma, both B- and T-cell types, and particularly in angioimmunoblastic T-cell lymphoma (AITL)." (PMID 25632305, 2015). "For example, the R550* nonsense mutation is the most frequent TET2 somatic mutation reported in myeloid malignancy (47/3035) and is also reported in lymphoma, astrocytoma, colorectal adenocarcinoma, endometrioid clear cell carcinoma, and squamous cell carcinoma of the upper aerodigestive tract." (PMID 40116537, 2025). "Furthermore, these lymphomas exhibit a congruent mutational spectrum, notably featuring loss-of-function mutations in genes associated with methylation, such as TET2, identified in approximately 80% of instances, and DNMT3A, observed in 30–40% of cases." (PMID 38365716, 2024). "The mutational landscape of TFH lymphoma includes genes involved in epigenetic pathways such as TET2 (up to 90%), IDH2 (20–45%), and DNMT3A (20–30%), mutations in the small GTPase RHOA (50–70%) and mutations in the TR signaling pathway including PLCG1, CD28, FYN, and VAV1." (PMID 37747559, 2024).
lymphoma (continued). "TET2 mRNA expression before the vitamin C trial appeared similar in unaffected individuals with and without TET2 mutation, whereas individuals previously affected by lymphoma displayed reduced TET2 expression." (PMID 36639817, 2023). "Given these pleotropic roles TET2 may play in the tumor microenvironment, it is important to carefully analyze the tumor-intrinsic versus microenvironmental roles TET2 loss-of-function mutations play in promoting nodal TFH lymphomas." (PMID 37841428, 2023). "TET2 mutations seem slightly more frequent in TFH lymphoma, NOS." (PMID 36793612, 2023). "Detecting TET2-CH may provide important information to identify lymphoma patients at increased risk of AIC." (PMID 35492814, 2022). "NGS of the RMH lymphoma panel revealed multiple mutations in TET2 (n = 4) and DNMT3A (n = 1), which were identical in both LN specimens and microdissected CD8+ T cells, with similar VAFs, and these changes were confirmed by Fluidigm PCR/Illumina MiSeq sequencing." (PMID 35064935, 2022). "Germline TET2 loss of function causes childhood immunodeficiency and lymphoma." (PMID 36203205, 2022). "The finding that the Tet2 gene itself showed impaired connectivity with upstream and downstream enhancers and reduced expression in Smc3wt/– murine lymphomas further underlines the potential mechanistic and biological links between Tet2 and cohesin complex in GC lymphomagenesis." (PMID 34621263, 2021). "Taken together with our transcriptional profiling showing enrichment for Tet2 and Kmt2d deficient signatures, these data suggest that reduced levels of Smc3 in lymphomas impairs expression and functionality of tumor suppressor genes through disruption of enhancer-promoter interactions." (PMID 34621263, 2021). "However, the authors identified a new TET2 mutation in the clone representing the lymphoma by targeted exome sequencing." (PMID 33939308, 2021). "This may be by reason for the behavior of Tet2 in various types of immune-cell subsets, and it might explain why some patients with Tet2 mutations stay healthy, whereas others develop either myeloid or lymphoid cancer." (PMID 33184433, 2020). "In addition, loss-of-function mutations of TET2 are quite frequent in lymphomas with follicular helper T-cell-like characteristics." (PMID 33160401, 2020). "Here, we discover a germline TET2 mutation in a lymphoma family." (PMID 30890702, 2019). "In humans, TET2 mutations are frequently associated with age-related clonal hematopoiesis, and children carrying autosomal recessive mutations in TET2 exhibit skewed T-cell development, altered B-cell maturation, and a pronounced susceptibility for development of lymphomas." (PMID 34413196, 2021). "Interestingly, most DNMT3A mutations in Tfh lymphomas occur together with TET2 mutations." (PMID 32704161, 2020). "In AITL, the lymphoma associated TET2 and DNMT3A mutations most likely occur at an early stage of hematopoiesis because these mutations are also present in non-tumoral hematopoietic cells of patients, thereby raising the possibility that they may be early events in oncogenesis." (PMID 33292562, 2020). "In their research, hypermethylation of the Bcl6 locus followed by Bcl-6 upregulation, combined with TET2 mutations, was thought to be the key event for lymphoma development which may result in biased Tfh differentiation and eventually contribute to AITL/PTCL development in patients." (PMID 30828337, 2019). "WGBS data, created from the three lymphoma-free TET2delA carriers and three age-matched controls, were used for genomic enrichment analyses due to the higher number of data points and because the chromatin annotation of affected regions after TET2 loss is likely identical in different cell types." (PMID 30890702, 2019). "The next-generation sequencing performed on the sample confirms that the predominant T-cell clones in this lymphoma contained CAR-T cell fusion mRNA, with potential driver mutations found in TET2, BRAF (V600E), PPM1D, ATM, and RUNX1." (PMID 41509667, 2026).
lymphoma (continued). "For example, mutations in TET2 and DNMT3A are frequently observed in CD4 + T-helper cell-derived lymphomas, such as angioimmunoblastic T-cell lymphoma." (PMID 41431105, 2025). "DNMT3A or TET2 gene mutations were detected in AML, lymphoma, or myeloma patients, with equal prevalence." (PMID 40869343, 2025). "In T-cell lymphoma patients, the DNMT3A mutation was detected in both T-lymphoma cells and the CD19+ blood fraction, whereas the TET2 mutation was shared between neoplastic clone, B cells and HSPCs." (PMID 38440231, 2024). "Up to 80% of patients with TFHL have underlying CH, with shared TET2 and/or DNMT3A mutations in the early progenitor cells (i.e., hematopoietic stem cells) as well as the lymphoma." (PMID 37500795, 2023). "TET2 is present in 50-90% of cases, DNMT3A and IDH2 are seen on 20% to 55% of cases An inactivating RHOA mutation can be seen in 70% of TFH lymphoma -AITL subtype and usually co-occurs with TET2 mutations." (PMID 37188189, 2023). "In several sequencing studies of nodal TFH lymphomas including AITL, multiple TET2 mutations were found in individual tumor samples implying a strong selective pressure." (PMID 37841428, 2023). "Despite frequent TET2 mutations in a wide array of T cell lymphomas, most commonly in nodal TFH lymphomas, it was initially unclear the degree to which TET2 loss-of-function directly contributed to lymphomagenesis." (PMID 37841428, 2023). "Recurrent somatic mutations in multiple epigenetic regulators, including loss-of-function mutations in TET2, inactivating mutations in DNMT3A and neomorphic mutations in IDH2, have been strongly associated with nodal TFH lymphomas." (PMID 37841428, 2023). "Studies of linage specific-knockout mice suggest that Tet2 regulates dynamic lineage commitment and differentiation at multiple differentiation stages and represses leukemia/lymphoma development." (PMID 36203205, 2022). "Using hierarchical clustering, they identified a cluster (cluster 1) that is enriched in cases with both TET2 and RHOA mutations, with a subset harboring IDH2 mutations as well, indicative of AITL and other Tfh-like lymphomas." (PMID 35954378, 2022). "In fact, TET2 inactivation leads to polyhematopoietic abnormalities in mice, which is a recurrent event in human lymphoma formation." (PMID 35309925, 2022). "Similar to other lymphomas, mutations of genes that regulate the epigenome are frequent in PTCL, and loss of function mutations in the TET2 gene is likely to be a founder mutation in angioimmunoblastic lymphoma (AITL)." (PMID 35954378, 2022). "To date, the prognostic significance of TET2 dysregulation in NHL is still not well characterised and further understanding of epigenetic drivers of TET2 regulation in lymphoma requires additional investigation." (PMID 34899857, 2021). "Since the role of Tet2 as an epigenetic regulator is well known, the methylation profile was studied in the lymphomas of these mice." (PMID 32796826, 2020). "This suggests that TET2 deficiency contributes to the formation of AITL and Tfh-like lymphoma (lymphoma with follicular helper T-cell-like features)." (PMID 33160401, 2020). "Remarkably, most of the AITL patients carrying the RHOAG17V mutation also have TET2 mutations indicating a cooperation between these two mutations in disrupting normal CD4 T-cell phenotype and function in this aggressive lymphoma." (PMID 32796826, 2020).
lymphoma (continued). "In this context, our finding of the lymphoma‐associated TET2 mutation in an independent minor T‐cell population is not totally a surprise, but this raises an interesting question about whether the same TET2 mutation may initiate an independent lymphomagenic process." (PMID 31859368, 2020). "As TET2 mutations are frequently detectable in multipotent hematopoietic stem cells, it is not surprising that patients with myeloid and lymphoid cancers frequently share a clonal origin." (PMID 40116537, 2025). "Additionally, some of these patients exhibited early hematopoietic clones, diagnosed with lymphoma or secondary AML, with TET2 mutations consistently detected across all these conditions." (PMID 41451201, 2025). "In the case with composite EMZL and EBV‐positive DLBCL (case 6), both lymphomas harboured 23 common variants, including mutations in CD274, TET2, and TNFRSF14, and the EBV‐positive DLBCL showed an additional MYC translocation and a further 20 variants over the EMZL component." (PMID 39722652, 2025). "When patient’s own T-cells already harbor the DMNT3A or TET2 mutations, the resulting CAR-T cells might be source of secondary CAR-positive T-lymphomas, however such cases seems to be very rare." (PMID 38440231, 2024). "In lymphomas, the epigenetic modifiers ten-eleven translocation 2 (TET2), DNA methyltransferase 3A (DNMT3A), and isocitrate dehydrogenase 2 (IDH2) are commonly mutated and correlate with heightened hypermethylation of genes involved in TCR signaling and T cell differentiation." (PMID 37239368, 2023). "Mutations in the epigenetic regulator TET2 are among the most frequent mutations identified in PTCL, with the highest frequency in angioimmunoblastic T cell lymphomas and other nodal T follicular helper (TFH) lymphomas." (PMID 37841428, 2023). "TET2 is a tumor suppressor gene, catalyzing DNA demethylation, LOF mutations are particularly common in follicular helper T-cell (Tfh) lymphomas, and TET2 deficiency might contribute to the formation of AITL and Tfh-like lymphomas." (PMID 36239901, 2022). "However, these mutations are also commonly observed in other blood malignancies, including B and T lymphomas, such as the angioimmunoblastic T-cell lymphoma (AITL), showing the highest incidence of TET2 mutations (roughly 80%) among all blood cancer types." (PMID 35159097, 2022). "In some cases of lymphoma and MM, gene mutations in DNMT3A or TET2 were the only detected events." (PMID 33436578, 2021). "Besides, Tet2 downregulation was vital for 5-hydroxymethylcytocine (5hmC) regulation in adult T-cell leukemia/lymphoma (ATLL) progression and Tet2-KO mice developed myeloid cancers with an incidence rate of about 30%." (PMID 34615554, 2021). "Conditional knock-out alleles have been successfully employed to study the in vivo role of many lymphoma-associated tumor suppressor genes encoding for transcription factors (BLIMP1), epigenetic modifiers (EZH2, CREBBP, KMT2D, TET2), small G proteins (GNA13) and ubiquitin ligases (FBXO11)." (PMID 34456919, 2021). "A patient with AITL and a patient with CLL had loss of function TET2 mutations, which indicates sensitivity towards DNMT inhibitors such as Decitabine or Azacitidine, which both are tested in clinical trials for treatment in different lymphoma sub types." (PMID 32013121, 2020). "In our study, we included KMT2D, CREBBP, EZH2, EP300, MEF2B, and TET2 in our lymphoma panel." (PMID 31403034, 2019). "Of note, in AITL and related lymphomas, RHOA mutations were accompanied by TET2 mutations, suggesting that TET2 and subsequent RHOA mutations may pave the way for T-cell transformation." (PMID 29148847, 2018).